STK11 (serine/threonine kinase 11)
Diseases named in the same sentence as STK11 in open-access papers (continued):
Sharing a sentence is not in itself a finding about the gene and the disease.
breast cancer (continued). "The present study used mouse breast cancer cell lines to investigate phenotypic alterations in response to Stk11 knockout." (PMID 41051525, 2025). "In conclusion, we found that Stk11 knockout in breast cancer cells enriches immune-related pathways." (PMID 41051525, 2025). "Knockout of the Stk11 gene was performed by sgRNA transfection in three mouse breast cancer cell lines: M158, NF639, and PY8119." (PMID 41051525, 2025). "In the present study, we investigate downstream effectors of STK11 suppression using RNA sequencing and cytokine array analysis in murine breast cancer cell lines." (PMID 41051525, 2025). "In breast cancer, STK11/AMPK signaling has been shown to inhibit TGF-β transcription and downstream Smad phosphorylation, modulating TGF-β-mediated responses." (PMID 41051525, 2025). "In our study, knockout of Stk11 in murine breast cancer cell lines resulted in significant enrichment of cytoskeleton-related gene (Bpifb4), and cell adhesion/migration-related genes (Cdh5, Plat, and Pmp22), along with enhanced tumorigenicity in vivo." (PMID 41051525, 2025). "In this study, we established Stk11-knockout (Stk11-KO) mouse breast cancer cell lines, performed RNA sequencing and cytokine array analysis to assess alterations in gene expression and cytokine profiles." (PMID 41051525, 2025). "A potential link between inactivation of STK11 and immune response regulation has been suggested in breast cancer, but the impact of STK11 suppression on tumor–immune interactions remains under investigation." (PMID 41051525, 2025). "Another important obesity-related cytokine, adiponectin, was found to be capable to induce autophagic cell death in breast cancer cells through STK11/LKB1-mediated activation of the AMPK-ULK1 axis." (PMID 37274250, 2023).
breast cancer (continued). "In Jamaica, we found a 5.5% (10 of 183) rate of inherited breast cancer with germline variants in BRCA1, BRCA2, PALB2, STK11, and NBN genes." (PMID 33646313, 2021). "A study focusing on the molecular mechanisms ADIPOQ participated in has revealed that ADIPOQ induces cytotoxic autophagy in breast cancer cells through STK11/LKB1-mediated activation of the AMPK-ULK1 axis." (PMID 33717664, 2021). "HNK upregulates expression of STK11 and higher expression of STK11 positively correlates with breast cancer prognosis." (PMID 32963809, 2020). "Recent study from our group reported that STK11 plays an important role in mediating anti-cancer effects of HNK leading to inhibition of cancer stem-like phenotype in breast cancer by direct inhibition of oncogenic Stat3 signaling." (PMID 32963809, 2020). "Together, these results confirm that breast cancer cells undergo autophagy in a STK11-dependent manner." (PMID 32963809, 2020). "In conclusion, we present that breast cancer cells invoke cytoprotective autophagy in response to HNK treatment via STK11 whose expression is a key node for autophagic induction." (PMID 32963809, 2020). "We also show that tumor suppressor STK11 is important for initiating autophagy in HNK-treated breast cancer cells as STK11 silencing abrogates LC3B-II puncta, autophagosome/lysosome fusion and lysosomal activity." (PMID 32963809, 2020). "The serine/threonine protein kinase 11 (STK11) gene is a highly penetrant breast cancer gene that regulates energy metabolism and cell polarity." (PMID 31379942, 2019). "Mutations in high-risk breast cancer genes or genes associated with syndromic diagnoses (CDH1, PALB2, PTEN, STK11, and TP536, 20, 21) were identified in 1.4% of the FBC cohort." (PMID 28649662, 2017). "In breast cancer, STK11 IHC showed the existence of different prognostic value between cytoplasmic STK11 and nuclear STK11." (PMID 26625312, 2017). "STK11 is frequently lost in human breast cancers but was found amplified in three of the five canine tumors." (PMID 24098698, 2013).
breast cancer (continued). "The genes CD44 (P = 0.050), RARB (P = 0.026), ATM (P = 0.017) and STK11 (P = 0.040) also showed less frequent methylation in male breast cancer." (PMID 22765268, 2012). "We used CRISPR/Cas9 single-guide RNA to knock out the Stk11 gene in mouse breast cancer cell lines." (PMID 41051525, 2025). "Tumors derived from Stk11-KO mouse breast cancer cells demonstrated greater tumorigenicity." (PMID 41051525, 2025). "Moreover, analysis of breast cancer patient samples showed an inverse association between the plasma CXCL1 levels and STK11 expression." (PMID 41051525, 2025). "Based on these findings, we hypothesized that downregulation of STK11 in breast cancer cells activates immune-related pathways and fosters an immunosuppressive microenvironment, thereby promoting tumor progression." (PMID 41051525, 2025). "The results confirmed the clinical significance of low STK11 levels in breast cancer patients." (PMID 41051525, 2025). "Moreover, researchers have shown that adiponectin can induce autophagy in breast cancer cells by activating the AMPK-ULK1 axis mediated by serine/threonine kinase 11 (STK11)/liver kinase B1 (LKB1), which, in turn, promotes breast cancer cell apoptosis." (PMID 38813109, 2024). "Distribution of VUS in breast cancer predisposing genes were :APC:1(5.8%), ATM:2(11.7%), BRCA1:1(5.8%), BRCA2:5(29.4%), BRIP1:1(5.8%), CDKN2A:1(5.8%), CHEK2:2(11.7%), FANC1:1(5.8%), MET:1(5.8%), STK11:1(5.8%), NF2:1(5.8%)." (PMID 37277882, 2023). "Based on the CNV data, several special CNV regions were identified, including gain peaks containing known breast cancer driver genes such as ERBB2 and NOTCH2, as well as the loss peaks containing some known tumor suppressor genes such as PRDM16 and STK11 (CNV focal peak gene annotation)." (PMID 35013309, 2022). "Other genes: Pathogenic variants in BRIP1, RAD51C, RAD50, NBN, STK11, and RECQL may also confer some level of breast cancer risk." (PMID 34439109, 2021).
breast cancer (continued). "We raised the question whether STK11 plays any role in autophagy induction in breast cancer cells treated with HNK." (PMID 32963809, 2020). "Collectively, the in vitro and in vivo findings presented here reveal that breast cancer cells initiate a cytoprotective autophagic response in a STK11-dependent manner to evade HNK efficacy which can be potentiated by combining an autophagy inhibitor with HNK treatment." (PMID 32963809, 2020). "STK11/LBK1 mutations have been detected to be related to estrogen-receptor positivity, which may work as causative factor of breast cancer in susceptible people." (PMID 30975222, 2019). "That is, CDH1 and STK11 have a limited contribution to breast cancer in unselected Japanese women." (PMID 30287823, 2018). "Thus, there is evidence of PTEN-SSL activity of STK11 in a large pan-cancer patient cohort, and breast cancers within the cohort showed a similar pattern consistent with PTEN-STK11 SSL interaction." (PMID 29566768, 2018). "STK11 is a candidate gene for breast cancer (BC) with the highest prediction score." (PMID 30598097, 2018). "Another gene in the 19p-region that may appear as a suitable candidate is the STK11/LKB1 gene that is associated with the Peutz-Jehger's syndrome, in which breast cancer is a frequent manifestation." (PMID 19077293, 2008). "Besides, the autophagy activator adiponectin ADIPOQ and 2-aminonicotinonitrile compound (w09) significantly inhibit breast cancer growth by stimulating autophagy through the serine/threonine kinase 11 (STK11)-AMPK-ULK1 and EGFR-mediated RAS-RAF1-MAP2K-MAPK1/3 pathway, respectively." (PMID 35725836, 2022). "Therefore, our focus was on STK11-low rather than STK11-mutated breast cancers." (PMID 41051525, 2025). "Other interesting observations included the mutual exclusivity of KEAP1 and STK11 in NSCLC and enrichment for CDH1, PIK3CA, and ARID1A along with mutual exclusivity with BRCA1/2, PTEN, and ESR1 in breast cancer." (PMID 40178042, 2025). "In the current Swedish national breast cancer guidelines the syndrome genes with a very low frequency of findings (CDH1, PTEN, STK11) have been excluded from the routine clinical gene panel." (PMID 37563628, 2023). "It has been demonstrated that adiponectin induces autophagic cell death in breast cancer through activation of the AMPK-ULK1 axis, which is regulated by STK11/LKB1." (PMID 37454080, 2023). "The promoter of STK11, a high penetrance breast cancer gene, was commonly hypermethylated in WTC-exposed breast cancer cases compared to exposed cancer-free controls." (PMID 35564499, 2022). "In addition, the pathogenic variant carriers for PTEN, CDH1, and STK11 identified from unselected breast cancer patients in this study did not meet the criteria for the Cowden syndrome, hereditary diffuse gastric cancer syndrome, and Peutz-Jeghers syndrome, respectively." (PMID 34606182, 2021). "We next performed an in silico analysis of mRNA expression levels in patient-derived samples and observed that in prostate carcinomas and certain breast carcinomas, PIM expression was elevated and LKB1/STK11 expression was reduced." (PMID 34193159, 2021).
breast cancer (continued). "Four of these five patients—two with cervical cancer, one with breast cancer, and one with germline cancer—had at least two molecular alterations involving the PI3K/AKT/mTOR pathway, including STK11 and INPP4B." (PMID 32914004, 2018). "Given that STK11/LKB1, CDKN2A, and PTK6 each have well-described roles in cancer progression, we hypothesized that PAQR8 might play a role in breast cancer recurrence." (PMID 36597146, 2023). "Mutations in ARID1A are frequent in non-small cell lung cancer, colon cancer, bladder cancer and breast cancer, whereas mutations in KEAP1 and STK11 was predominate in non-small cell lung cancer (8.62% and 11.75%, respectively)." (PMID 34302033, 2021). "Additional larger case-control studies or segregation analysis in families might be needed to fully elucidate the breast cancer risks for PTEN, CDH1, and STK11 in Chinese women." (PMID 34606182, 2021). "The present study shows the complexity of this pathway as HNK-mediated upregulation of STK11 also supports a negative feedback loop triggering a cytoprotective autophagy in addition to stimulating breast cancer cell death." (PMID 32963809, 2020). "However, no study directly correlates STK11 expression in breast cancers with their relationships with tumor-infiltrating immune cells." (PMID 41051525, 2025).